CD101 (CD101 molecule)
Diseases named in the same sentence as CD101 in open-access papers (continued):
Sharing a sentence is not in itself a finding about the gene and the disease.
Bovine mastitis (1 paper, 2023). INFLAMMATION of the UDDER in cows. "For many of the genes that overlapped with dMHB discriminant signatures in this study, such as ZNF691, MAML2, ZC2H7B, CD101, TSPAN32, and MAML2, this is the first report of their involvement in bovine mastitis." (PMID 37373515, 2023).
colon cancer (1 paper, 2023). "Therefore, we believe that CD39+CD101+CD8+Trm could better predict the tumor reactivity of CD8+TIL in colon cancer." (PMID 37675100, 2023).
diabetes (1 paper, 2019). "Protection from diabetes was associated with a significantly reduced infiltration of pancreatic islets by immune cells in CD101-expressing congenic mice at 8–10 weeks of age." (PMID 31199784, 2019). "The mechanisms by which Cd101 variants interfere with autoimmune responses will allow us to understand the regulation of molecules in autoimmunity in general as diabetes susceptibility loci have been associated with other autoimmune diseases." (PMID 31199784, 2019). "Contemporaneously, cohorts of CD101+/+ and CD101−/− NOD.B6 Idd10 mice as well as CD101+/+ and CD101−/− NOD.B6 Idd10 progeny from heterozygous CD101+/− NOD.B6 Idd10 intercross breeders were monitored for diabetes." (PMID 31199784, 2019). "CD101+/− NOD.B6 Idd10 heterozygous progeny had a diabetes frequency intermediate between those of CD101+/+ and CD101−/− NOD.B6 Idd10 progeny." (PMID 31199784, 2019). "Indeed, CD101−/− NOD.B6 Idd10 mice and CD101−/− NOD.B6 Idd10/18 mice had frequencies of diabetes equivalent to that of NOD mice housed in the same colony." (PMID 31199784, 2019).
disseminated candidiasis (1 paper, 2016). Systemic candidiasis occurs when Candida yeast enters the bloodstream and may spread (becoming disseminated candidiasis) to other organs, including the central nervous system, kidneys, liver, bones, muscles, joints, spleen, or eyes. "In this disseminated candidiasis study, in which only a single dose was administered, the prolonged efficacy may be the result of a longer plasma half-life of CD101 in comparison with other echinocandins." (PMID 27620474, 2016).
HIV-1 infection (1 paper, 2017). The type species of lentivirus and the etiologic agent of acquired immunodeficiency syndrome (AIDS). "Our replication of CD101 Ig-like variants showed an HR for HIV-1 infection of 4.3 (95% CI = [2.1–8.9], p = 6.4x10-5); and replication of association of UBE2V1 rs6095771 with HIV-1 acquisition risk showed an HR of 6.4 in women (95% CI = [2.1, 19.1], p = 9.5x10-4)." (PMID 29108000, 2017). "Hence, these variants or others in CD101 and UBE2V1 could have a substantial impact on the population-based HIV-1 infection risk." (PMID 29108000, 2017).
inflammatory bowel disease (1 paper, 2018). A spectrum of small and large bowel inflammatory diseases of unknown etiology. "Notably, reduced expression of CD101 has been detected in inflammatory bowel disease (IBD) patients." (PMID 29851958, 2018).
ischemia (1 paper, 2021). A hypoperfusion of the BLOOD through an organ or tissue caused by a PATHOLOGIC CONSTRICTION or obstruction of its BLOOD VESSELS, or an absence of BLOOD CIRCULATION. "The present study demonstrated for the first time that CD101 can be used as a marker to define the maturation status of neutrophils mobilized into the peripheral blood in response to ischemia and recruited to sites of ischemic injury after reperfusion." (PMID 34289931, 2021).
melanoma (1 paper, 2025). A malignant, usually aggressive tumor composed of atypical, neoplastic melanocytes. "The immature precursor subset hNeP (CD117+CD66b+), lacking maturation markers CD10 and CD101, exhibited the strongest phagocytic capacity, comparable to monocytes, and was significantly expanded in advanced melanoma, suggesting an association with tumour progression." (PMID 41451221, 2025).
multiple myeloma (1 paper, 2022). "CD38+CD101+ T cells, which characterize a permanently dysfunctional population of T cells, previously linked to post-stem cell transplant relapse in multiple myeloma, were present in 22.02 ± 7.6% of late relapsed multiple myeloma CAR T cells compared with 6.39 ± 0.9% in HD products (NS)." (PMID 36874402, 2022).
myocarditis (1 paper, 2025). Myocarditis is a condition that is characterized by inflammation of the heart muscle (myocardium). "Based on the transcriptional profile and surface assessment of CD274 and CD101, our data show that eosinophils in the heart of hypereosinophilia-associated myocarditis are type 1 polarized." (PMID 41050650, 2025).
pancreatic cancer (1 paper, 2021). "CD8+, CD101+ T-cells expressing CD38 and PD-1 have been associated with poor prognosis in pancreatic cancer." (PMID 32661823, 2021).
primary immunodeficiency (1 paper, 2022). "Moreover, KEGG analysis suggested that cytokine–cytokine receptor interaction, ECM–receptor interaction, transcriptional misregulation in cancer, pathways in cancer, chemokine signaling pathway, and primary immunodeficiency were potential pathways in regulating CD101 expression." (PMID 35350788, 2022).
pulmonary disease (1 paper, 2024). "To investigate whether CD101+ eosinophils are universally involved in pulmonary inflammatory responses, we analyzed eosinophils in other eosinophil-related pulmonary disease models induced by chitin and papain." (PMID 39214980, 2024).
Stroke (1 paper, 2024). Sudden impairment of blood flow to a part of the brain due to occlusion or rupture of an artery to the brain. "Our proteomics analysis shows the downregulation of CD101 also in young mice, indicating a broader role of such neutrophil phenotypes in stroke pathophysiology." (PMID 39395581, 2024). "Furthermore, atypical, transcriptionally immature neutrophils were found in aged mice after stroke, aggravating stroke pathology, in which CD101- cells were the key regulators." (PMID 39395581, 2024).
viral infection (1 paper, 2022). "As suggested by the differentiation state of these cells and previous reports of CD101 expression on CD8 in viral infection, we demonstrate that CD101+ CD4 T cells are highly enriched for expression of immunosuppressive receptors in lymphoid tissue during ART." (PMID 35867722, 2022). "While CD101 has been investigated in chronic viral infection on CD8 T cell populations using the LCMV mouse model, its role on CD4 T cells has not been investigated in the rhesus macaque model and there have been no studies of CD101+ CD4 T cells in acute and chronic viral infection." (PMID 35867722, 2022). "Collectively, these observations suggest CD101-expressing cells represent a functionally distinct population of CD4 T cells that can play a key role in regulating inflammatory environments, such as those after a viral infection." (PMID 35867722, 2022).
tumor (39 papers, 2016 to 2026). "Mature neutrophils express cell-surface CD101, whereas immature CD101– neutrophils are associated with tumor progression." (PMID 36453551, 2022). "Results from enrichment analyses manifested that CD101 predominantly expressed on the tumor-associated macrophages and was significantly associated with the immune regulatory processes, as evidenced by its positive correlation with immune-related genes and the putative infiltration of immune cells." (PMID 35350788, 2022). "Likewise, results of the GSEA analysis revealed that upregulated CD101 expression was associated with immunoregulatory interactions between a lymphoid and a non-lymphoid cell and interactions between immune cells and microRNAs in the tumor microenvironment." (PMID 35350788, 2022). "Our findings indicated that CD79A, COL5A1, ERO1A, and GJB2 were significantly overexpressed in tumor tissues compared to normal tissues, while CD101 and CPA3 showed more active expression in normal lung tissues, aligning with our prior analysis." (PMID 39850883, 2024). "The CD101 upregulation on the AH1-tet- TILs is likely due to the presence of other than AH1-specific tumor-reactive CD8+ T cells among the sorted PD1+CD8+ TILs." (PMID 37045833, 2023). "Analysis of tetramer+ TILs from triple-treated mice in both tumor models showed that the percentage of polyfunctional (IFNγ+TNF+) cells decreased from the TCF1+TIM3-PD1+ to the CD101-TCF1-TIM3+PD1+ to the CD101+TCF1-TIM3+PD1+ subset." (PMID 37045833, 2023). "Our results showed that the expression of CXCR2 and CD101 in peripheral blood G-MDSCs of tumor-bearing mice was reduced." (PMID 35013108, 2022). "In a mouse model of orthotopic pancreatic cancer, the presence of immature neutrophils defined as Ly6Glow/+CXCR2− CD101− increased in tumor-bearing mice, and mice with higher tumor burden showed higher infiltration of immature neutrophils into the pancreas." (PMID 35158948, 2022). "In our tumor model, we observed that anti-PD-1 treatment induced a subtle increase in the percentages of terminally exhausted CD101+ TIM3+ cells in both WT and Suv39h1KO CD8+ TILs." (PMID 35768432, 2022). "The bystander memory TIL population also contained a significantly lower frequency of CD38 and CD101 double-positive cells compared to the tumor-specific T cells, thus indicating that bystander memory cells in the TME are resistant to terminal differentiation." (PMID 34867942, 2021). "CD101 (IGSF2) was identified as a possible marker to distinguish transitionally exhausted T cells, which still exert anti-tumor activities by invigoration from terminally exhausted T cells." (PMID 33535613, 2021). "Recent study in mice showed that CD101 segregates immature neutrophils from mature neutrophils during G-CSF stimulation and in the tumor setting." (PMID 34289931, 2021). "Tumor antigen specific CD8 T cells in dLNs, however, showed a very low frequency of CD8 T cells associated with a terminally exhausted phenotype (CD38+CD101+ TCF1lo)." (PMID 32391270, 2020). "In 2019, Zhang and his team found that CD38/CD101 co-repression on tumor-infiltrating lymphocytes were related with a poor survival in PDAC patients." (PMID 33062410, 2020). "Determining the phenotype of tumor-antigen-specific CD8+ T cells with impaired Roquin-1/Regnase-1 interaction in the tumor we found that these cells showed greatly reduced expression of the exhaustion markers CD101, PD1 and Tox." (PMID 35251035, 2022). "To verify our hypothesis, we analyzed the expression of PD-1 and CD101 in tumor-infiltrating CD38+ CD8+ T cells and CD38− CD8+ T cells by flow cytometry." (PMID 33934206, 2021). "However, despite the significantly increased expression of PD-1 and CD101, tumor-infiltrating CD3+ CD+ T cells still retained a higher ability to secrete cytotoxic-related cytokine and killing tumors." (PMID 33934206, 2021).
tumor (continued). "Interestingly, we found that the frequency of CD101+CD38+ tumor specific CD8 T cells was significantly lower in cells isolated from the tumors of FOLFOX-treated mice." (PMID 32391270, 2020). "High CD38/CD101 co-expression by PD-1+ CD8+ T cells in the peripheral blood of PCa patients or tumor-infiltrating lymphocytes (TILs) in PCa tissues correlated significantly with tumor/node/metastasis (T/N/M) classification, and with clinical stage and survival." (PMID 34439378, 2021). "In the tumor immune microenvironment, CD8 + TIM3 + CD101 + T cells (CCT cells) play a pivotal role in tumor progression and immune evasion." (PMID 40375334, 2025). "These TCF1+ PD1+ cells differentiate into the effector-like “transitory” CD101- TIM3+ PD1+ subset originally described in the model of lymphocytic choriomeningitis virus (LCMV) 29 and later found in mouse tumor models." (PMID 38646638, 2024). "We observed this relationship even in a group-to-group comparison, in which the CD101/Ly6G or CD101/Ly6C values were higher in the BRQ-treated, tumor-bearing mice compared with the vehicle controls." (PMID 36453551, 2022). "We also provide evidence suggesting stark differences between the path to T cell dysfunction in ccRCC and that in other tumor types or in chronic infection at the level of TFs (for example, TBX5) and surface markers (for example, CD101)." (PMID 35668194, 2022). "Plasticity of T cells (defined by higher levels of Tcf1 and lower levels of PD1, CD38, CD101, CD39, and TIGIT) has emerged as a significant factor in their function in vivo in viral and tumor models." (PMID 33320837, 2021). "It further converts immature (CD101-) and mature (CD101+) neutrophils into a CD14+ICAM-1+ subset through STING-NF-κB-TNF-α signaling, enhancing tumor infiltration and antitumor activity." (PMID 41854362, 2026). "Additionally, we found more tumor-specific T cells with a stem-like (TCF1+ TIM3- PD1+) and a transitory (TCF1- TIM3+ CD101- PD1+) exhausted phenotype and more expressing effector molecules such as GzmB, IFNγ, and TNFα." (PMID 38646638, 2024). "By performing differentially expressed gene (DEG) analysis, we found that many immunosuppressive and exhaustion-related genes such as LAG3, CD101, SMAD2, and ID1, which was one type of the mediators of tumor progression, were highly expressed in PBMCs from RTP patients." (PMID 34687295, 2021). "In line with our hypothesis, we found that tumor-infiltrating CD3+ CD+ T cells expressed higher level of PD-1 and CD101 than that in normal tissues." (PMID 33934206, 2021). "Tumor specific CD8 T cells with plastic and fixed exhaustion programs can be distinguished phenotypically depending on the expression of CD101 and CD38 (high in terminally exhausted CD8 T cells) and the transcription factor TCF-1 (low in terminally exhausted CD8 T cells)." (PMID 32391270, 2020). "While we found the strongest expansion of triple treatment-induced tumor-specific T cells in blood, we also observed substantial expansion of the CD101-negative subset of PD1+TIM3+ TILs, i.e., of transitory cells which are non-terminally differentiated (effector-like) exhausted cells." (PMID 37045833, 2023). "Strikingly, CD101, a type I transmembrane glycoprotein, was highly co-expressed with CD103 in both the tumor and tumor adjacent skin but not in the TdLN, suggesting that CD101 as a potential marker to identify TRM-like cells." (PMID 41279375, 2025). "Different phenotypes of Th17 cells, especially CD39+CD101+PD1+ Th17 cells, may be critical for the prediction of tumor-reactive TILs; however, such studies are currently lacking." (PMID 37675100, 2023).
infection (7 papers, 2017 to 2025). The state of being infected such as from the introduction of a foreign agent such as serum, vaccine, antigenic substance or organism. "Notably, we found that lower levels of CD101+ cells in RB 14 days post-infection was significantly associated with a higher fold-change of zonulin from pre-infection to day 42 post-infection." (PMID 35867722, 2022). "The idea that CD101 expression is associated with preferential infection and depletion is additionally supported by two independent studies in which genetic variants in the CD101 locus are associated with altered immune activation and increased risk of sexually acquired HIV infection." (PMID 35867722, 2022). "Building upon data from the previous imaging panel and our flow cytometry data, we also observed a significantly higher number of CD3+ and CD101+ cells in the lungs of PBS-vaccinated NC99-challenged primary infection mice." (PMID 41190814, 2025). "It is difficult to assess direct cell death in vivo, and therefore we cannot say for certain that CD101 cells are preferentially depleted due to increased infection and cell death." (PMID 35867722, 2022). "The contribution of CD101+ cells within each subset to the overall pool of CD4 T cells was also fully restored to pre-infection levels." (PMID 35867722, 2022). "This increase was accompanied by a shift from a predominately mature population of CD101+ neutrophils within the blood three hours post-infection (98.5 ± 1.2% of total neutrophils) to an immature CD101- subset (65.7 ± 10.9% of total neutrophils) (p < 0.0001)." (PMID 32882969, 2020). "The new member of this drug class, CD101, displays extraordinary penetration attributes at the site of infection relative to micafungin." (PMID 28739797, 2017). "After long-term ART, CD101+ CD4 T cells are restored to pre-infection levels, harbor intact SIV DNA at levels comparable to those found in the other memory CD4 T cells, and are enriched in inhibitory markers suggestive of a potential for long-term maintenance of the latent viral reservoir." (PMID 35867722, 2022). "CD4 loss was calculated based on absolute counts of CD101+ CD4 pre- and post-infection." (PMID 35867722, 2022). "Unfortunately, given the very low levels of CD101+ CD4 T cells after infection, we are unable to sort these cells and directly assess whether they harbor more virus at this time." (PMID 35867722, 2022). "The outstanding penetration of CD101 at the site of infection is dose dependent." (PMID 28739797, 2017). "CD101+ CD4 T cells are severely depleted during acute SIV infection (14 days post-infection), with a mean 2.6-fold reduction in the frequency of blood memory CD4 T cells expressing CD101." (PMID 35867722, 2022). "CD101+ eosinophils have also been observed during breakthrough infection by our group, although they did not appear to correlate with host pathology." (PMID 41190814, 2025). "Within 24 hours of infection, most recruited neutrophils exhibited an immature phenotype, as indicated by their lack of expression of CD101." (PMID 36139433, 2022). "Moreover, the high plasma drug exposure of CD101 (area under the concentration-time curve from 0 to 168 h [AUC0–168] of 813 μg · h/ml for 200 mg and 1,840 μg · h/ml for 400 mg) and its distribution to sites of infection are promising." (PMID 29133552, 2018). "Additionally, although our in vitro infection model does not show increased infection levels of CD101+ CD4 T cells, this model may not fully replicate the phenotypic environment of these cells during in vivo infection, particularly given the role of CD101+ cells in the gut." (PMID 35867722, 2022). "Between three- and 24-h post-infection with VSV, the majority of neutrophils in the bone marrow had adopted an immature phenotype, as indicated by their lack of expression of CD101." (PMID 32882969, 2020).
infection (continued). "To assess whether CD101 is being downregulated on CD4 T cells after infection rather than these cells being directly depleted, we evaluated CD101 surface levels after in vitro HIV infection of sorted CD101- and CD101+ CD4 T cell cultures." (PMID 35867722, 2022).
cancer (3 papers, 2016 to 2022). A tumor composed of atypical neoplastic, often pleomorphic cells that invade other tissues. "Specific surface markers proposed to identify neutrophil subsets in cancer include CD101 and CD177, which are associated with cancer regression, and CD117, PDL1, CD170, LOX1, CD84 and JAML, which are associated with T cell immunosuppression and cancer progression." (PMID 34674757, 2021). "By contrast, CD101, which has been reported as a potential risk-associated variant for PDAC, plays a role as an inhibitor of CD3-induced T-cell proliferation, and so the variants of this gene may have the immuno-modulatory effect on cancer cells." (PMID 27613834, 2016).
CD101 also shares sentences with these, for which no sentence is quoted: prostate carcinoma (6 papers); type 1 diabetes (3); osteosarcoma (2); vulvovaginal candidiasis (2); acute myeloid leukemia (1); allergic asthma (1); astrocytoma (1); bacterial infections (1); bladder cancer (1); B‐cell lymphoma (1); Chronic colitis (1); COVID-19 (1); diffuse large B-cell lymphoma (1); embryonal rhabdomyosarcoma (1); gout (1); helminth infections (1); leukemia (1); low grade glioma (1); lymphoid neoplasm (1); mesonephric adenocarcinoma (1); metastatic carcinoma (1); neuritis (1); neuropathy (1); nosocomial infection (1); oligodendroglioma (1); rheumatoid arthritis (1).